CD68 (CD68 molecule)
Diseases named in the same sentence as CD68 in open-access papers (continued):
Sharing a sentence is not in itself a finding about the gene and the disease.
atherosclerosis (continued). "L-sel deletion did not result in an altered CD68 positive area in either early (71.10%±1.36% vs 74.44%±2.90%; p = n.s.) or advanced atherosclerosis (48.20%±4.13% vs 39.62%±1.99%; p = n.s.)." (PMID 21760899, 2011). "Multiplex immunohistochemistry analyses have shown increased infiltration of CD3+ T cells, CD20+ B cells, CD68+ macrophages, and CD15+ neutrophils within the intima of diseased coronary arteries compared to normal arteries, indicative of an active immune response in atherosclerosis." (PMID 41409744, 2025). "Simple linear regression analysis of plaque CD68 area showed a substantial difference in the rates of plaque macrophage accumulation between weight cycling and noncycling, indicating that WR accelerates atherosclerosis progression." (PMID 40627456, 2025). "In recipient mice transplanted with old bone marrow, atherosclerosis regression was impaired, as evidenced by inefficient resolution of circulating inflammatory cell levels, reduced activation of plaque autophagy and apoptotic cell clearance, and persistent plaque CD45+ and CD68+ content." (PMID 39945065, 2025). "Similarly, the extent of atherosclerosis of other aorta sites, including AA, TA, abdominal aorta, and brachiocephalic artery, were evaluated by H&E staining, Masson's trichrome staining, and IHC (MMP-9, CTSK, CD68, and α-SMA)." (PMID 35673565, 2022). "Also, the total macrophages (CD68+), M1 pro-inflammatory macrophages (MHC-II+), and the immune cell infiltrate represented by T lymphocytes (CD3e+) that support the inflammatory process characteristic of atherosclerosis were followed." (PMID 35478972, 2022). "On the contrary, trehalose influenced neither the progression of atherosclerosis (“cross section”: 271325.4 ± 7225.5 μm2 vs 275830.8 ± 12676.9 μm2; p > 0.05) nor the content of macrophages (CD68 staining: 45.25% ± 1.7% vs 45.52% ± 3.4%; p < 0.05) in apoE−/− mice fed an HFD." (PMID 30925684, 2019). "The control RCA presents as a normal vessel, suggesting that atherosclerosis was not systemically developed in this model, whereas the diseased LCAs show atypical cell proliferation and accumulation of macrophages and lymphocytes via H&E, Trichrome, and CD68 stains." (PMID 34944397, 2021). "As the expression pattern of CAIX in atherosclerosis was unknown, and macrophages are the predominant hypoxic cells expected to express CAIX, we performed double immunohistochemical staining for CAIX and CD68 to evaluate their co-localization in human unstable carotid plaques." (PMID 33432108, 2021). "However, there were more CD68-positive macrophages and ICAM-1-expressing cells in plaques from apoE−/−/PGC-1α−/− mice compared to those from littermate controls, implicating a potential role of macrophage PGC-1α in atherosclerosis in vivo which is in keeping with the data presented above." (PMID 23964012, 2013). "Compared with normal mice (−K/BxN serum -HFD), the populations of CD3+/CXCR3+ cells, CD68+ macrophages, CD3+ T cells of atherosclerosis mice (−K/BxN serum + HFD) did not exhibit any significant differences." (PMID 39716053, 2024).
melanoma (103 papers, 2006 to 2026). A malignant, usually aggressive tumor composed of atypical, neoplastic melanocytes. "Across various cancer types, including non-small cell lung cancer (NSCLC), ovarian, gastric, melanoma, and breast cancers, CD68 expression is associated with a poorer prognosis and reduced survival rates." (PMID 39717759, 2024). "The second marker whose positivity was significantly linked with shorter PFS in patients with malignant melanoma was CD68 expression." (PMID 36980787, 2023). "RNA-seq and IHC analysis of 57 human melanoma samples showed that CD68+ TAMs were associated with increased iNOS and arginase expression." (PMID 36686729, 2022). "A dense CD163+ve MΦ infiltration in melanoma stromal tissue and CD68+ve MΦ infiltration at the invasive front were associated with poor overall survival." (PMID 34831352, 2021). "A recent report found high expression of CD68+ TAMs to be associated with recurrence of melanoma, and other studies have reported the clinical and functional significance of CD68+ TAMs in GC, though without addressing the M1 and M2 subsets." (PMID 31521128, 2019). "Analyzing tumor-associated macrophages (TAMs) labeled with CD68, we found that several melanomas (MEL) that were CD68-hot were CD8-cold which was rarely observed in other tumor types." (PMID 30179157, 2018). "Furthermore, CD8+ CTLs associated positively with IDO+ stromal immune and melanoma cells and tumor nest CD68+ macrophages, but only weakly with FoxP3+ Tregs and total macrophage counts." (PMID 36551965, 2022). "However, high CD68+ HLA-DR+ macrophages are associated with better prognosis in melanoma." (PMID 35158883, 2022). "A lower frequency of CD68+ macrophages has also been observed in studies of patients with liver metastasis from colorectal cancer and melanoma patients." (PMID 39456610, 2024). "Inflammatory cells, including Cd68+ macrophages and S100a8+ neutrophils were similarly present in the lungs at baseline and 6 h post melanoma injection, and were excluded from the analysis." (PMID 39627185, 2024). "TAMs in melanoma are a diverse and constantly changing group, with a subset of unpolarized CD68+/CD163–/iNOS– macrophages consistently existing." (PMID 39703508, 2024). "Studies have shown that invasive melanomas have a greater quantity of CD68+ and CD163+ TAMs in comparison to benign nevi." (PMID 39703508, 2024). "Anti-CTLA4 immunotherapy can significantly deplete CD68 macrophage in patients with advanced melanoma compared to the untreated sample group." (PMID 39499374, 2024). "At present, a number of studies have reported that CD14+ or CD68+ macrophages have been observed to up-regulate the expression of PD-L1 in a variety of cancer tissues, including hepatocellular carcinoma, melanoma and ovarian cancer." (PMID 39003253, 2024). "In the meanwhile, there was a strong correlation between the expression of CMTM6 and that of CD3+ T cells, CD20+ B lymphocytes, and CD68+ macrophages in melanoma." (PMID 37726578, 2023). "Costaining analysis of CD206/CD68 showed that the melanomas of Colec11–/– mice exhibited lower numbers of CD68+ cells than WT controls." (PMID 36883567, 2023). "On the other hand, proteomic analysis of human melanoma cell lines indicated that all of them expressed CD68 protein." (PMID 36754910, 2023). "Particularly, VISTA was described as a potent inhibitory checkpoint on CD68+ macrophages when comparing an immunotherapy-sensitive tumor (melanoma, n = 44) with an immunotherapy-resistant tumor (pancreatic cancer, n = 67)." (PMID 37190254, 2023). "Previous studies have confirmed that high-density invasion of CD68+ TAMs in TN was associated not only with OS, PFS, and specific survival in patients with melanoma but also with disease free survival in patients with endometrial cancer." (PMID 36910657, 2023).
melanoma (continued). "Costaining analysis of MHC class II (H2-Ab1)/CD68 showed that the melanomas of Colec11–/– mice exhibited lower numbers of CD68+ cells again but higher percentage of H2-Ab1+ cells and higher intensity of H2-Ab1 in CD68+ cells than WT controls." (PMID 36883567, 2023). "This is in contrast to our data showing an elevated number of CD68+ macrophages in B16 melanomas after Gal1 vaccination." (PMID 35018481, 2022). "GLP decreased the count of CD68+ macrophages in melanoma tissues and inhibited melanoma growth in vivo, thus prolonging the survival rate of tumor-bearing mice." (PMID 35865946, 2022). "Along the same lines, pancreatic tumor tissue was divided into cancer region, pancreatic tissue, duct epithelium, stroma, and melanoma lymph node tissue was classified into CD68 + compartment, CD45+ compartment, and tumor compartment." (PMID 35590346, 2022). "GrB+ lymphocytes associated positively with PD-L1+ tumor and stromal immune cells (p-values 0.009 and 0.027, respectively), IDO+ melanoma cells (p < 0.001), and tumor nest CD68+ and CD163+ macrophages (p-values 0.002 and 0.003, respectively) (data not shown)." (PMID 36551965, 2022). "At least in the B16 melanoma model used in this study, F4/80 and CD68 identify largely overlapping populations of macrophages." (PMID 35018481, 2022). "The infiltration of CD68+CD16+ classically activated M1 macrophages was higher in melanoma tumors that responded to anti-CTLA-4." (PMID 36435510, 2022). "An increase in CD68+ macrophages within inguinal TDLNs was also observed in B16-F10 mouse melanoma-bearing mice following repeated injection of anti-4-1BB mAb." (PMID 32868911, 2021). "On the other hand, we observed that β2M and PD1 are positively correlated with CD8 only in melanoma, while the macrophage marker CD68 is negatively correlated with CD8 only in GBM." (PMID 34188042, 2021). "Melanoma, on the other hand, is typically positive for c-kit, CD68, S-100, HMB-45, Melan-A, throsinase, and vimentin, and negative for smooth muscle actin, desmin, chromogranin, and epithelial membrane antigen." (PMID 33478436, 2021). "A higher number of CD68+ve TAMs has been reported with increasing depth of melanoma invasion and ulceration and in malignant compared to benign melanocytic lesions." (PMID 34831352, 2021). "The authors questioned the specificity of CD68 as it can be detected in lymphomas, carcinomas, and up to 70 percent of melanomas as reported in one case series." (PMID 34449584, 2021). "First, we established conditions to quantify by multicolor fluorescent-microscopy the content of CCL20, TNF, and VEGFA in CD68+ cells in FFPE melanoma tissues." (PMID 34439098, 2021). "In contrast, melanoma tissue showed a massive accumulation of CD68-positive immune cells, many proliferating cells and an increased immunoreactivity for granzyme-B and α-SMA." (PMID 34544377, 2021). "Some studies of CD68+ TAM involving patients with melanoma, gastric and colorectal cancer reported contrasting findings." (PMID 34089486, 2021). "In fact, and at the protein level, FRβ expression was observed in CD163+ cells in melanoma and in areas enriched in CD68+ cells in colon adenocarcinoma." (PMID 32532019, 2020). "NHWD-870 also decreased the number of TAMs (CD11b+F4/80+ cells) or proliferating TAMs (CD11b+F4/80+CD68+Ki67+ cells) in A375 melanoma model." (PMID 32286255, 2020). "Fifty-seven formalin-fixed, paraffin-embedded primary melanomas were analysed by immunohistochemical analysis of CD68, CD163, inducible nitric oxide synthase (iNOS) and arginase expression." (PMID 32843682, 2020). "Primary untreated melanoma lesions were stained with CD68 and CD163 antibodies to identify macrophage populations, and the number of positive cells per mm2 was measured in both intratumoural tissue and peritumoural tissue." (PMID 32843682, 2020). "IHC with CD68, which reacts with macrophages, aids the discrimination of melanoma cells from macrophages." (PMID 32143442, 2020).
melanoma (continued). "CD68 and Melan A were used to highlight the macrophages and melanoma cells, respectively, if necessary." (PMID 32143442, 2020). "Next, we stained human melanoma sections and located P2Y12 on a subset of CD68+ macrophages in human primary as well as skin metastatic lesions of melanoma." (PMID 31591378, 2019). "With the help of this antibody, P2Y12 expression was confirmed on CD68+ CD163+ TAM of melanoma in situ." (PMID 31591378, 2019). "Human malignant melanoma tissues exhibited increased CD68+-macrophage infiltration and NFAT1 expression compared with the normal pigmented nevus tissues." (PMID 30459241, 2018). "Human malignant melanoma tissues exhibited increased infiltration of CD68+ TAMs and NFAT1 expression compared with the normal pigmented nevus tissues." (PMID 30459241, 2018). "In this study, we observed that human malignant melanoma tissues exhibited increased infiltration of CD68+ macrophages and NFAT1 expression compared with the normal pigmented nevus tissues." (PMID 30459241, 2018). "The sequential staining of these samples revealed that in all naevi samples LYVE-1+ macrophages were present, while only in 73.3 % of primary melanoma samples and in 72.4 % of the metastasis CD68/LYVE-1 double positive cells were spotted." (PMID 29262593, 2017). "Microscopic findings and the presence of histiocytic cells led to the performance of an immunohistochemical staining panel using monoclonal antibodies for S-100, CD1a, pan-cytokeratin, CD-68, melanoma marker (HMB45) and melanoma A protein." (PMID 26749317, 2016). "Monoclonal antibodies for S-100, CD1a pan-cytokeratin, CD-68, melanoma marker (HMB45) and melanoma A protein were included in this panel." (PMID 26749317, 2016). "We found a higher percentage of CD163+ TAMs than of CD68+ TAMs in both thymoma and thymic carcinoma samples, which was consistent with previous observations in Hodgkin’s lymphoma, malignant melanomas, and leiomyosarcomas." (PMID 25499804, 2014). "In melanoma, for instance CD68+ TAMs in the TN positively correlated with both poor OS and RFS, however it did not fall out as an independent risk factor upon multivariate analysis." (PMID 22824040, 2012). "While CD68 is a marker for cells of the monocyte/macrophage lineage, it is relatively nonspecific, with reported staining in neoplasms such as carcinoma, melanoma, angiosarcoma, lymphoma, and schwannoma." (PMID 22289504, 2012). "Analysis of macrophage infiltration in relation to the American Joint Committee on Cancer (AJCC, 8th edition) staging system revealed a general trend of increasing CD68+ macrophage density in both intratumoral and peritumoral compartments as melanoma progressed." (PMID 41007741, 2025). "Similarly, in melanoma, an abundance of CD68+ macrophages correlates with a poorer prognosis and increased melanoma-specific mortality." (PMID 39717759, 2024). "High numbers of CD68+ macrophages inside tumor cell nests are linked to recurrence, while a low proportion of CD163+ macrophages in the tumor stroma is related to recurrence and, in initial melanomas, also with poor overall survival." (PMID 39703508, 2024). "The intratumoral ratio between CD8+ and CD68+ cells, which is predictive of long-term survival in primary melanoma, also failed to associate with regional progression in this cohort." (PMID 38361951, 2024). "For instance, benign granular cell tumors are positive for S-100 protein, CD63, CD68 and neuron-specific enolase whereas atypical fibroxanthoma stains negatively for S100 protein, Melan-A, human melanoma black (HMB)-45 pan-cytokeratin (CK) and actin and positively for CD68 and vimentin." (PMID 36832159, 2023). "The expression of CD68+ lymphocytes proved its predictive value only in malignant melanoma." (PMID 36980787, 2023). "However, different from a previous study, we only found a tendency to an increased density of CD68+ve TAMs from dermal and dysplastic nevi to pT1 and pT4 melanomas." (PMID 34831352, 2021).
melanoma (continued). "The number of CD68+ve TAMs increases with increasing melanoma invasion and ulceration." (PMID 34831352, 2021). "Moreover, RET melanoma cells were detected inside macrophages, as was demonstrated by co-localization of CD68 macrophage and mCherry RET cells with fragmented condensed nuclei." (PMID 34282238, 2021). "In addition to the positive correlations of CD68+ macrophages with iNOS+ cells and iNOS+ cells with BRAF status, we found that there were a significantly higher number of CD68+ macrophages in BRAF+ melanomas." (PMID 32843682, 2020). "Moreover, other immune cells presented higher CD68 (M0 macrophages), and Foxp3 (Tregs) expression in melanoma tissues than in healthy skin tissues." (PMID 32931642, 2020). "Moreover, IFNγ signatures (CXCL10, CXCL9, IDO1, IFNG, and STAT1) and myeloid lineage phenotypic and functional markers (CD14, CD163, CD33, and CD68) were also significantly increased in melanoma patients with high ETV7." (PMID 33424867, 2020). "The authors suggested that some of these cells might represent macrophage-melanoma hybrids, such as a CD68 protein that is co-expressed with MART-1 mRNA." (PMID 32182935, 2020). "We detected P2Y12 in CD68+ CD163+ TAM of primary melanoma as well as melanoma metastases." (PMID 31591378, 2019). "Moreover, NFAT1 overexpression in melanoma-conditioned TAMs promoted CD68+-macrophage infiltration, tumor growth, and metastasis in vivo." (PMID 30459241, 2018). "Although we found an association between CD68+ macrophages and high PDCD4 expression using QIF, PDCD4 was not present at high levels in the macrophage (defined as CD14+/C1QA−) or microglia (defined as C1QA+) populations in our one sequenced melanoma brain metastasis sample." (PMID 33801444, 2021). "Similarly, some melanoma–monocyte hybrids were positive for CD68." (PMID 27271591, 2016). "The annotated FOVs of the tissue samples had enriched sinuses were subjected to analysis, revealing an increase in macrophage markers (CD68 and CD163) within the LN sinuses of melanoma patients." (PMID 41271007, 2025). "To validate that these cells were indeed melanophages, we immunostained three independent patient specimens with a melanoma marker HMB45, the mature melanosome marker GPNMB, and a pan-macrophage marker CD68." (PMID 38719996, 2024). "SpatialDB was used to determine the overlap between the distributions of CD74, the macrophage marker CD68, and the M1 macrophage marker CD86 in PRAD and melanoma tissues." (PMID 38582956, 2024). "In patients with malignant melanoma, we found shorter PFS related to FoxP3 nuclear positivity (17.0 vs. 4.5 months, p = 0.048, HR 3.04, 95% CI 0.95–9.71) and CD68 positivity (15.0 vs. 4.1 months, p = 0.034, HR 3.21, 95% CI 1.02–10.1)." (PMID 36980787, 2023). "Quantification of CD56/MLANA double-positive melanoma cells, MLANA+ melanoma cells, CD68+ macrophages, and CD8+ T-cells in five regions of interest (ROI) showed that on average 13% of all MLANA+ cells (3,171 cells) were CD56/MLANA double-positive (430 cells)." (PMID 37563418, 2023). "M1/M2 phenotypes of TAMs in the melanomas of WT and Colec11–/– mice were further evaluated by IHC costaining of CD206/CD68 or H2-Ab1/CD68." (PMID 36883567, 2023). "The panel included the immune cell markers CD8, CD68, CD16, the immune checkpoint PD-L1, and melanoma tumour marker SOX10." (PMID 35664673, 2022). "The BF multiplex IHC staining was performed using different combinations of six immune-cell markers—CD3, CD4, CD8, CD20, CD68 and CD163—and the melanoma cell marker SOX10." (PMID 35954345, 2022). "Here, we evaluate the presence of CD68+ and CD163+ macrophages in FFPE human primary melanoma lesions and determine their correlation with the functional canonical M1:M2 enzymes inducible nitric oxide synthase (iNOS) and arginase." (PMID 32843682, 2020).